MB (myoglobin)
Diseases named in the same sentence as MB in open-access papers (continued):
Sharing a sentence is not in itself a finding about the gene and the disease.
infection (13 papers, 2010 to 2026). The state of being infected such as from the introduction of a foreign agent such as serum, vaccine, antigenic substance or organism. "The inflammatory storm caused by infection will also further damage the organs, resulting in increased myoglobin." (PMID 39164612, 2024). "Acute myocardial injury biomarkers, including cardiac troponin I, CK-MB, and myoglobin, increased significantly from pre-infection baseline to the terminal endpoint for rabbits pretreated with c-IgG." (PMID 37781371, 2023). "MPO and VCAM-1 were also positively correlated with Hispanic ethnicity in this group, and myoglobin was significantly elevated in fatal infection." (PMID 37598150, 2023). "Resistin, IL-6, and myoglobin were all positively correlated with each other in fatal infection." (PMID 37598150, 2023). "Analogously, Anis13 (myoglobin), one of the major antigens of A. pegreffii, genetically characterised, is identified as a target of IgE immune response during the human infection by the L3 stage of A. pegreffii." (PMID 37009516, 2023). "The severe infection group demonstrated significantly elevated circulating levels of myoglobin, VCAM-1, and MPO which were significantly correlated with severe infection." (PMID 37598150, 2023). "Myoglobin (p = 0.02), VCAM1 (p < 0.0001), and myeloperoxidase (MPO) (p < 0.0001) were all significantly upregulated in the plasma of the severe infection group compared to healthy controls." (PMID 37598150, 2023). "Neutrophilia, low MHCII expression by monocytes, and elevated plasma Resistin, IL-6, myoglobin, and VCAM-1 correlated with fatal infections." (PMID 37598150, 2023). "However, in our infection model, probably as consequence of different experimental conditions and the parasite and mouse strain used, we were unable to detect, by ELISA, anti-myosin, anti- myoglobin and anti-skeletal muscle antibodies in sera of acutely-infected mice (day 15 p.i.)." (PMID 20454564, 2010). "The significant prevalence of infection (particularly pulmonary infection) and AKI in the RML group underscores the systemic impact of skeletal muscle injury, which may be driven by myoglobin toxicity and inflammatory cascade reactions." (PMID 41584825, 2026). "In contrast, cardiac troponin I, but not CK-MB or myoglobin, increased significantly from pre-infection baseline to the terminal endpoint for rabbits pretreated with anti-Hla/Luk/ClfA mAb combination." (PMID 37781371, 2023).
cardiac disease (6 papers, 2008 to 2025). "The efficiency of the ZnO nanorod treated paper as protein concentrator was successfully tested for myoglobin, a biomarker for heart disease." (PMID 28252113, 2017). "As a medical application, continuous label-free detection of creatine kinase and myoglobin (two cardiac disease biomarker proteins) was demonstrated using a microcantilever biosensor array functionalized with anti-creatine kinase and anti-myoglobin whole antibodies." (PMID 40277531, 2025). "First, when the clinical symptoms of UA and NSTEMI are quite similar, we found that patients with a history of heart disease are more likely to have NSTEMI, and a series of cardiac biomarkers will be different, including the common Myoglobin, CK-MB, hs-cTnI, NT-proBNP(p < 0.001)." (PMID 39451645, 2024). "Myoglobin has long been considered a marker of myocardial injury; however, it is sensitive but not specific for cardiac disease." (PMID 39164612, 2024).
kidney (4 papers, 2017 to 2025). "Glycerol‐induced rhabdomyolysis leads to muscle cell damage, releasing myoglobin into the bloodstream and causing kidney damage." (PMID 39803217, 2025). "Therefore, we subjected human renal proximal tubular epithelial cell line (HK-2) to myoglobin to mimic rhabdomyolysis-associated kidney injuries in vitro." (PMID 28383559, 2017). "Myoglobin is responsible for the main mechanisms of acute kidney injury development, including myoglobin-induced renal vasoconstriction, direct injury to tubular cells, and the formation of tubular casts." (PMID 32679822, 2020).
neurological diseases (2 papers, 2021 to 2023). "Therefore, for those who have previous neurological diseases and long-term oral intake of drugs that can cause RM, creatine kinase and myoglobin should be detected regularly to be alert for the development of RM." (PMID 37808625, 2023).
brain disease (1 paper, 2024). "Among them, 8 differential urinary proteins were previously reported to be closely associated with brain disease, including NP, FZD1, B2M, EPCR, ATRN, MB, CA1and VPS4A." (PMID 38836960, 2024).
MB also shares sentences with these, for which no sentence is quoted: acute myocardial infarction (31 papers); liver failure (6); Hypocalcemia (5); stable angina (5); bacterial infection (3); cardiac arrest (3); dengue (3); leukopenia (3); neuroleptic malignant syndrome (3); serotonin syndrome (3); ST Elevation Myocardial Infarction (3); ventricular fibrillation (3); acute pancreatitis (2); adenocarcinoma (2); aortic regurgitation (2); benign tumor (2); Brain Injuries (2); cardiac hypertrophy (2); cerebrovascular disease (2); Cirrhosis (2); dilated cardiomyopathy (2); Hypercholesterolemia (2); Hypoalbuminemia (2); Insulin resistance (2); metabolic syndrome (2); pericarditis (2); peripheral arterial disease (2); sarcomatoid carcinoma (2); sarcopenia (2); schizophrenia (2).
A further 84 diseases each share a sentence with MB in 2 papers or fewer.